ACOXL (acyl-CoA oxidase like)
Synonyms: FLJ11042; ACOX4
Tractability: No criterion of Open Targets' tractability assessment is met for any kind of drug.
Gene: Protein-coding gene on chromosome 2 (110,732,524 to 111,118,548, forward strand). Ensembl gene ENSG00000153093.
Subcellular location (Human Protein Atlas): Cytosol; Nucleoli
Pathways (Reactome):
Metabolism: Beta-oxidation of pristanoyl-CoA
Gene Ontology:
Molecular function: fatty acid binding; flavin adenine dinucleotide binding; acyl-CoA oxidase activity; FAD binding; oxidoreductase activity, acting on the CH-CH group of donors
Biological process: fatty acid beta-oxidation using acyl-CoA oxidase; fatty acid beta-oxidation; fatty acid metabolic process
Cellular component: cytosol; peroxisomal matrix; peroxisome
Genetic constraint (gnomAD): Loss-of-function variants: 67 observed, 66.26 expected, observed/expected ratio (o/e) 1.01, 90% interval 0.83 to 1.24. The upper end of that interval is the gene's LOEUF score, 1.24, which puts it in group 5 of 6, group 1 being the genes least tolerant of losing a copy. Missense variants: 680 observed, 742.47 expected, observed/expected ratio (o/e) 0.92, 90% interval 0.86 to 0.98. Synonymous variants: 249 observed, 282.02 expected, observed/expected ratio (o/e) 0.88, 90% interval 0.8 to 0.98.
Homologues: Orthologues: dog ACOXL (90% identical), pig ACOXL (84% identical), mouse Acoxl (74% identical), rat Acoxl (73% identical), tropical clawed frog acoxl (71% identical), rabbit ACOXL (69% identical), zebrafish acoxl (60% identical), Caenorhabditis elegans acox-1.1 (21% identical), Caenorhabditis elegans acox-1.4 (21% identical), Caenorhabditis elegans acox-1.2 (20% identical), Caenorhabditis elegans acox-1.3 (19% identical), Caenorhabditis elegans acdh-1 (14% identical), and 3 more. Paralogues in human: ACOX1 (22% identical), ACOX3 (22% identical), ACOX2 (22% identical), ACAD9 (16% identical), ACADVL (16% identical), ACADS (16% identical), ACADSB (15% identical), ACADM (14% identical), IVD (14% identical), ACAD11 (13% identical), ACAD8 (13% identical), ACADL (13% identical), and 2 more.
Diseases named in the same sentence as ACOXL in open-access papers:
ACOXL is named in the same sentence as 19 diseases in open-access papers, as found by Europe PMC text mining. Sharing a sentence is not in itself a finding about the gene and the disease. The quoted sentences say what the papers report.
prostate carcinoma (4 papers, 2015 to 2023). A carcinoma that arises from epithelial cells of the prostate gland. "Recently, an enrichment of the ACOXL gene has been implicated in prostate cancer serum using metabolic quantitative trait loci analysis in the serum of 402 Swedish men." (PMID 26237329, 2015). "ACOXL is also downregulated in prostate cancer tissues, but further studies are required to confirm any potential role in tumourigenesis." (PMID 27490482, 2016). "Using this strategy TMEM79 and ACOXL were identified as two novel candidate biomarkers for prostate cancer." (PMID 26237329, 2015). "However, further analysis of TMEM79 and ACOXL at a number of levels including functional analysis, analysis of ACOXL expression levels in matched tissue and serum are warranted in prostate cancer tissue in order to determine if they have clinical impact in disease screening." (PMID 26237329, 2015). "Our data provides a starting point for further functional studies to explore the molecular repertoire of normal and diseased prostate including potential prostate cancer markers such as TMEM79 and ACOXL." (PMID 26237329, 2015). "Approximately 86% (132/154) benign prostate tissue samples had positive cytoplasmic ACOXL expression and approximately 72% (129/179) prostate cancer tissue samples did not express ACOXL, suggesting a high specificity and sensitivity also for ACOXL to identify benign prostate glands." (PMID 26237329, 2015).
Obesity (3 papers, 2022 to 2024). Accumulation of substantial excess body fat. "They identified 34 shared loci among 3 obesity-related traits and 2 asthma subtypes and, utilizing an obesity mouse model, identified 2 genes (acyl-coenzyme A oxidase-like (ACOXL) and myosin light chain 6 (MYL6)) playing a significant role in both diseases." (PMID 36013497, 2022).
alopecia areata (1 paper, 2021). Loss of scalp and body hair involving microscopically inflammatory patchy areas. "The chromosomal region where ACOXL resides (2q13) was also mapped as a possible susceptibility locus in human alopecia areata." (PMID 34445339, 2021).
atherosclerosis (1 paper, 2023). A disease characterized by the build-up of fatty material and calcium deposition in the arterial wall resulting in partial or complete occlusion of the arterial lumen. "IL17C and ACOXL were diagnostic genes of atherosclerosis and associated with higher incidence of ischemic events." (PMID 37173646, 2023). "In conclusion, we identified IL17C and ACOXL were diagnostic genes of atherosclerosis and associated with higher incidence of ischemic events." (PMID 37173646, 2023). "In this study, multiple machine learning methods (LASSO, RF, SVM-RFE) identified IL17C (AUC = 0.92) and ACOXL (AUC = 0.90) as novel diagnostic biomarkers for atherosclerosis, and verified in other datasets." (PMID 37173646, 2023). "Least absolute shrinkage and selection operator, random forest, support vector machine- recursive feature elimination show that IL17C and ACOXL were identified as diagnostic markers of atherosclerosis." (PMID 37173646, 2023).
gastric cancer (1 paper, 2025). A primary or metastatic malignant neoplasm involving the stomach. "By targeting metabolic pathways involving ACOXL, it may be possible to reverse the immune evasion and apoptosis resistance seen in gastric cancer, providing new avenues for treatment that directly address the metabolic reprogramming associated with cancer progression." (PMID 41292676, 2025).
gastric tumor (1 paper, 2025). "Taken together, these observations suggest that ACOXL‐driven perturbations of lipid catabolism may couple metabolic reprogramming to apoptosis resistance and immune evasion within the gastric tumor microenvironment, providing a mechanistic context for its adverse prognostic association." (PMID 41292676, 2025).
lymphoma (1 paper, 2025). A malignant (clonal) proliferation of B- lymphocytes or T- lymphocytes which involves the lymph nodes, bone marrow and/or extranodal sites. "Using exome sequencing, they identified six recurrent, rare, and potentially deleterious variants within 5 kb of lymphoma-associated GWAS loci in 75 MM cases (BTNL2, EOMES, TNFRSF13B, IRF8, ACOXL, TSPAN32)." (PMID 41300981, 2025).
prostate tumors (1 paper, 2015). "ACOXL displayed strong granular cytoplasmic expression in mitochondrial regions in approximately 86% of benign glands and this expression was lost in 72% of prostate tumors, corresponding to approximately 86% sensitivity and 72% specificity in identifying benign prostate glands in tissue." (PMID 26237329, 2015).
sarcoidosis (1 paper, 2025). Sarcoidosis is a multisystemic disorder of unknown cause characterized by the formation of immune granulomas in involved organs. "Finally, at least 8 additional genes have been implicated in immune regulatory response, whereas no clear evidence linking ACOXL, MAT1A, or MACROD1 to sarcoidosis or immune (dys)regulation was found from the available literature." (PMID 41466414, 2025). "Finally, no clear evidence linking ACOXL, MAT1A, or MACROD1 to sarcoidosis or immune (dys)regulation was found from the available literature." (PMID 41466414, 2025).
tumor (3 papers, 2015 to 2025). "This could suggest that the transformation in phenotype of normal epithelium to tumor epithelium may result in loss of ACOXL protein expression in the epithelium potentially due to leakage of ACOXL into the serum." (PMID 26237329, 2015). "Metabolic‐related genes such as PFKFB2 and ACOXL were upregulated in this group, underscores the paramount significance of sustaining metabolic stability in tumour biology." (PMID 40847563, 2025). "This insight into the role of ACOXL in immune evasion and tumor metabolism could guide the development of novel therapeutic strategies." (PMID 41292676, 2025).
cancer (1 paper, 2025). A tumor composed of atypical neoplastic, often pleomorphic cells that invade other tissues. "In vitro experiments implicated ACOXL in cancer cell evasion of apoptosis, supporting a role in pathogenesis." (PMID 41292676, 2025).
infection (1 paper, 2023). The state of being infected such as from the introduction of a foreign agent such as serum, vaccine, antigenic substance or organism. "We noted a high level expression of RRM2, MYBL2, and some other genes such as GALNT14, CENPU, ACOXL, and U2 at 0 weeks during active phase of infection, which were downregulated at 8 weeks after therapy." (PMID 37434783, 2023).
ACOXL also shares sentences with these, for which no sentence is quoted: asthma (2 papers); allergic asthma (1); Allergy (1); B-cell NHL (1); preeclampsia (1); T-cell NHL (1); type 1 diabetes (1).